PRKACA (protein kinase cAMP-activated catalytic subunit alpha)
Diseases named in the same sentence as PRKACA in open-access papers (continued):
Sharing a sentence is not in itself a finding about the gene and the disease.
pancreatic cancer (2 papers, 2021 to 2025). "The discovery of recurrent fusions involving NRG1 in KRAS wild-type pancreatic tumors, as well as case reports of fusions involving BRAF, PRKACA, NTRK1/3, and RET, prompted us to systematically screen for fusion genes in this cancer entity." (PMID 33441414, 2021).
adrenal cancers (1 paper, 2023). A carcinoma involving a adrenal gland. "An increasing number of studies have shown that PRKACA may promote the progression of cancer through kinases, such as PKA catalytic subunits, which are detected in the extracellular serum in various cancers, such as lymphoma as well as colon, kidney, rectal, prostate, lung, and adrenal cancers." (PMID 38201567, 2023).
asthenozoospermia (1 paper, 2025). "Likewise, in the infertility and asthenozoospermia disease network, PRKACA and SOD1 emerged as shared hub proteins." (PMID 41462610, 2025).
Carney complex (1 paper, 2022). Carney complex (CNC) is characterized by spotty skin pigmentation, endocrine overactivity and myxomas. "However, rare Carney Complex mutations are found in the catalytic Cα or Cβ subunits (encoded by PRKACA or PRKACB, respectively)." (PMID 36313756, 2022).
cervical cancer (1 paper, 2022). A primary or metastatic malignant neoplasm involving the cervix. "constructed a new prognosis predication model based on 8 risk-related PRGs (GPX4, GSDME, GZMA, GZMB, IL1B, NOD1, PRKACA, and TNF) in cervical cancer, which had good predictive ability (AUC = 0.794)." (PMID 35912258, 2022).
cholangiocarcinoma (1 paper, 2024). A carcinoma that arises from the intrahepatic biliary tree (intrahepatic cholangiocarcinoma) or from the junction, or adjacent to the junction, of the right and left hepatic ducts (hilar cholangiocarcinoma). "Also, our previous analyses revealed that a subset of cholangiocarcinoma tumors characterized by the ATP1B1-PRKACA fusion, which retains the same PRKACA exons as the DP fusion, express elevated levels of LINC00473." (PMID 38512964, 2024).
chronic heart failure (1 paper, 2023). "The activities of PRKAA1, PRKACA, and PAK1 were significantly enhanced in post-infarction chronic heart failure." (PMID 37405054, 2023). "Expression levels of PRKAA1, PRKACA, and PAK1 were increased in post-infarction chronic heart failure rats." (PMID 37405054, 2023). "PRKAA1, PRKACA, and PAK1 might serve as potential therapeutic targets for post-infarction chronic heart failure." (PMID 37405054, 2023).
Ellis-van Creveld syndrome (1 paper, 2026). Ellis-van Creveld syndrome (EVC) is a skeletal and ectoderlam dysplasia characterized by a tetrad of short stature, postaxial polydactyly, ectodermal dysplasia, and congenital heart defects. "Pathogenic missense variants in PRKACA cause craniofacial, skeletal, and cardiac defects similar to Ellis-van Creveld syndrome." (PMID 42157491, 2026).
endometriosis (1 paper, 2024). The growth of functional endometrial tissue in anatomic sites outside the uterine body. "Moreover, cyto-hub gene analysis revealed that CSNK2A1, CSNK2A2, TOP1, PRKACA, RBM39 (plasma), ALB, ACTB, GAPDH, FN1, APOA1 (serum), S100-A9, CXCL1, IL1RN, CSTA, S100-A8 (menstrual blood) and THBS1, ALB, CD44, ANXA2, and LUM (urine) were the top 5 proteins expressed in women with endometriosis." (PMID 39061077, 2024).
familial tumor syndromes (1 paper, 2026). "PBMAH may also result from alterations in MC2R, PRKACA, and phosphodiesterase (PDE)11A genes, and it can occur as part of familial tumor syndromes such as McCune-Albright syndrome (GNAS), MEN1, familial APC, or hereditary leiomyomatosis and renal cell carcinoma (FH gene variant)." (PMID 41503047, 2026).
heart failure (1 paper, 2025). Inability of the heart to pump blood at an adequate rate to meet tissue metabolic requirements. "By using Cytoscape software (Version: 3.10.2) in conjunction with MCC algorithms of the CytoHubba plugin, we identified the top 5 hub genes within the network (IL1B, NFKB1, MAP2K1, PRKACA, and HSP90AA1), suggesting that these genes are potential targets for EMPA and MET in heart failure therapy." (PMID 40364820, 2025).
hyperlipidemia (1 paper, 2024). "The estrogen signaling pathway was regulated by CA binding to HSP90AA1, MMP2, RARA, PRKACA, ESR1, MMP9, and ESR2 in this present research, which underlies the improvements observed in hyperlipidemia and thrombosis." (PMID 38398534, 2024).
ischemic encephalopathy (1 paper, 2024). "RELA, AKT1, JUN, PRKACA, PTGS2, RAF1 and CHUK were identified as four key targets associated with ischemic encephalopathy." (PMID 38285889, 2024).
male infertility (1 paper, 2016). The inability of the male to effect fertilization of an ovum after a specified period of unprotected intercourse. "Thus, we suggest that arsenic-induced repression of VDAC3, PRKACA and GPD2 as well as the aberrant increase of L-tyrosine may disrupt the extent of protein tyrosine phosphorylation required for sperm capacitation, which then result in fertilization failure and male infertility." (PMID 27585557, 2016).
meningioma (1 paper, 2019). A generally slow growing tumor attached to the dura mater. "Next, a database reporting the expression level of different genes in 68 meningioma cases was interrogated with BioGPS to explore the relationship between PRKACA gene, coding for PKA CAT, and PKA regulatory subunits (PRKAR1A, PRKAR1B, PRKAR2A, and PRKAR2B) gene products." (PMID 31671850, 2019). "The positive correlation of PRKACA with NF2 gene expression, which is downregulated in meningioma, may support this view, as well as the negative correlation of PRKACA expression with the four upregulated genes typically found in recurrent meningiomas (CDC2, MLF1IP, CKS2, and PRC1)." (PMID 31671850, 2019).
myxoma (1 paper, 2025). A benign soft tissue neoplasm characterized by the presence of spindle and stellate cells, lobulated growth pattern, and myxoid stroma formation. "Studies have implicated recurrent somatic mutations in PRKAR1A, as well as alterations in cAMP pathway genes such as PRKACA and PDE11A, suggesting a shared pathogenic mechanism between sporadic and familial myxomas." (PMID 40264618, 2025).
osteoarthritis (1 paper, 2024). A noninflammatory degenerative joint disease occurring chiefly in older persons, characterized by degeneration of the articular cartilage, hypertrophy of bone at the margins and changes in the synovial membrane. "Compared to osteoarthritis animals before treatment, strong upregulation of PRKACA mRNA expression (approximately 3–5 fold change)." (PMID 39428571, 2024).
Osteopenia (1 paper, 2026). Osteopenia is a term to define bone density that is not normal but also not as low as osteoporosis. "This expands the phenotypic spectrum of pathogenic variants in PRKACA and suggests that affected individuals may require periodic screening for aortic and coronary dilation as well as osteopenia." (PMID 42157491, 2026).
ovarian tumors (1 paper, 2017). "TCGA studies indicate that PRKACA, a gene that encodes PKA's catalytic subunit, is amplified in 15% of ovarian tumors, in addition to the known amplification of EMSY in 11% of cases." (PMID 28099152, 2017).
papillary carcinoma (1 paper, 2022). A malignant epithelial neoplasm characterized by a papillary growth pattern. "ERBB3/ERBB4/RAF1 kinases were activated in papillary carcinoma compared to other variants, PAK3/PAK6/CDK1 kinases were activated in NOS, and PRKACA/PRKACB/PRKACG kinases were activated in differentiation variants." (PMID 35659036, 2022).
Parkinsonism (1 paper, 2021). Characteristic neurologic anomaly resulting from degeneration of dopamine-generating cells in the substantia nigra, a region of the midbrain, characterized clinically by shaking, rigidity, slowness of movement and difficulty with walking and gait. "Therefore, it is plausible that the differential phosphorylation of the perturbators of this protein, PRKACA, PRKAR2A, and PRKAR2B, produces its downregulation and may trigger Parkinsonism." (PMID 34066091, 2021).
psoriasis (1 paper, 2021). An autoimmune condition characterized by red, well-delineated plaques with silvery scales that are usually on the extensor surfaces and scalp. "PRKACA's downstream effects involve multiple pathways, including WNT signaling, a pathway directly related with cPLA2ɑ signaling, and psoriasis in general." (PMID 34877506, 2021).
tumor (65 papers, 2009 to 2026). "In order to investigate, a possible connection between reduced RIIβ protein levels in PRKACA mutated tumours and its subcellular localization in these tumours, we performed simultaneous fluorescence immunohistochemistry of RIIβ and the Golgi apparatus in a subset of 10 CPA (6 WT and 4 mutated)." (PMID 28250426, 2017). "Protein kinases such as ACVR2A and PRKACA participate in signaling pathways governing cell growth and differentiation, with their dysregulation contributing to tumor progression." (PMID 39273340, 2024). "To reiterate, the pro-migration/invasion characteristics of PRKACA, as found in this study, support a proposal for targeting PRKACA directly and/or the β-adrenergic pathway for treating tumor invasion." (PMID 39458904, 2024). "This deletion leads to the fusion of exon 1 in the heat shock protein DNAJB1 with exons 2–10 in PRKACA, the catalytic subunit of protein kinase A, thereby promoting tumor growth through the activation of the PRKACA protein kinase." (PMID 37761849, 2023). "Protein kinase cAMP‐activated catalytic subunit alpha (PRKACA) is closely related to tumour progression activated by cAMP." (PMID 34816605, 2022). "Based on the hazard ratio (HR), the downregulated PLCG1, CASP6, CASP4, and AIM2 were considered tumor suppressors, whereas the upregulated PRKACA, NLRP9, and BAK1 were regarded as oncogenes." (PMID 34805183, 2021). "The PRKACA kinase domain was also found to play an essential role in FL-HCC tumor formation, suggesting the potential for small molecule PRKACA-inhibitors as a therapy for FL-HCC." (PMID 35126101, 2021). "This is even more so with the demonstration that high PRKACA expression was associated with the tumor hallmark of invasion or migration, rather than proliferation, in the GC and CRC cohorts." (PMID 39458904, 2024). "However, this comparison allowed us to identify kinases, which show higher differential regulation in tumours than acute perturbation such as PRKACA, MAPK1 and MAPK3." (PMID 36688815, 2023). "DMG single-cell RNAseq data showed PRKACA, and AKT1 were expressed preferentially in malignant cells while PAK2 was also present in the immune and oligodendrocytic populations suggesting targeting PAK2 can lead to off-tumor toxicity but PRKACA and AKT1 may be more selective targets." (PMID 39954016, 2025). "However, from another perspective, FN1, PRKACA were enriched in cancer pathways in this work, indicating that stemazole may affect the growth of hNSCs, instead of tumour cells, with a positive side." (PMID 35741576, 2022). "In addition, HSL in compact tumor cells was more abundant in CPA cases harboring PRKACA mt than non mt cases, which could contribute to the development of clinically more severe phenotypes such as higher serum cortisol levels and overt CS." (PMID 35216289, 2022). "The results showed that in the GC cohort, high PRKACA expression was significantly associated with the 60-years-and-below age group, higher nodal stage, and late disease stage but not with gender, histological tumor type, pathological tumor stage, or distant metastasis." (PMID 39458904, 2024). "The OS and the histological expressions of PRKACA and GPX4 in normal and tumor tissues were exhibited, in accordance with the results front." (PMID 35646872, 2022). "Based on the verification of the tissues from COAD patients by the method of qPCR, the results showed that CASP4, CASP5, PRKACA, and NOD1 were expressed differentially between normal and tumor tissues." (PMID 34938319, 2021). "Elevated CIDEA expression and diminished PRKACA, which phosphorylates and activates HSL, suggests that lipolysis was inhibited in tumour-bearing animals." (PMID 29258509, 2017).
tumor (continued). "PRKACA is the catalytic domain of protein kinase A and has been shown to be expressed in FLC but not in the adjacent normal liver, suggesting that this genetic alteration contributes to tumor pathogenesis." (PMID 39582856, 2024). "CASP3, SRC, ESR1, JAK2, PRKACA, HSPA8 and CAT exhibited stronger interactions with other factors, suggesting that they may be the key targets for tumor treatment." (PMID 38675723, 2024). "CARM1 or PRKACA KD led to a significantly smaller volume and lighter weight of tumor tissues compared with the negative control." (PMID 38201567, 2023). "Approximately one-third of the PA-ACS group harbour mutations of cortisol producing lines like PRKACA and GNAS with higher cortisol levels and tumour diameter than PA-ACS subjects without these mutations." (PMID 36428832, 2022). "In addition, tissue validation results also showed that CASP4, CASP5, PRKACA, and NOD1 were differentially expressed between tumor and normal tissues from COAD patients." (PMID 34938319, 2021). "A total of 24 pyroptosis-related genes shown significantly different expression between normal and tumor tissues in COAD and seven genes (CASP4, CASP5, CASP9, IL6, NOD1, PJVK, and PRKACA) screened by univariate and LASSO cox regression analysis were used to construct the risk model." (PMID 34938319, 2021). "We did not examine the specific cell types expressing PRKACA across the tissues, but in non-tumor brain cortex, the PRKACA expression was strongest in neurons." (PMID 27906173, 2016). "However, the roles of PRKACA in cancer are incompletely understood, inasmuch as the cyclic adenosine monophosphate (cAMP)-PKA signaling has been shown to possess both tumor-suppressive and oncogenic roles in different tumor types and contexts." (PMID 39458904, 2024). "Notably, this increase in fluorescence is seen in the tumor tissue in the cells that are characteristically FLC tumor cells (large, polygonal) and expressing high levels of PRKACA and not in the stromal cells (arrows)." (PMID 37343102, 2023).
cancer (56 papers, 2011 to 2025). A tumor composed of atypical neoplastic, often pleomorphic cells that invade other tissues. "We first analyzed the frequency of PKA-activating somatic alterations in the TCGA Pan Cancer Atlas, including both PRKACA gain-of-function and PRKAR1A loss-of-function mutations in addition to copy number alterations across multiple cancers." (PMID 36692000, 2023). "Further evidence suggested that the cAMP signaling pathway can be activated through PRKACA mutation in cancer." (PMID 26735889, 2016). "PHC3-PRKACA was classified as ‘cautionary’ PP-SV, as PHC3 showed a potential cancer suppressor effect in PCa, while PRKACA appears to portray oncogenic behaviour." (PMID 40064858, 2025). "PRKACA, which was hypermethylated among WTC-associated cancers, is vital for the attenuation of innate immune response, avoiding host damage during later stages of immune reaction." (PMID 38131903, 2023). "639V and Colo741 have been profiled for PKA dependency in the Cancer Dependency Map program, with Colo741 highly dependent on PRKACA." (PMID 36692000, 2023). "We found that the mRNA expression level of PRKACA was higher in the normal cell line than in the cancer cell lines, and for GPX4 it was the opposite, consistent with our results above." (PMID 35646872, 2022). "PRKACA, which participates in cellular processes, including differentiation, proliferation, and apoptosis, was significantly associated with CNV in 27 cancers." (PMID 35246158, 2022). "PRKACA has also been studied in the context of cancer, where its aberrant regulation and overexpression have been related to inflammatory activation of Caspase 1, oncogene activation, and elevated PGE2 levels." (PMID 34877506, 2021). "There are 36 protein kinases in the Cancer Gene Census; seven of them (EGFR, ERBB2, BRAF, FLT3, PRKACA, LCK, and FGFR2) had enriched PTM/mutation domains in our study." (PMID 29695735, 2018). "Activation of the PRKACA/AP-1 axis further promotes cancer cell migration and invasion." (PMID 40600138, 2025). "Overall, our findings suggest that the primary function of PRKACA in cancer may be pro-migration/invasion rather than cell proliferation in GI cancers and may explain the seemingly paradoxical roles that have been described for PRKACA in different cancers." (PMID 39458904, 2024). "In clinical cancer, PRKACA participates in a fusion event with DNAJB1 in up to a hundred percent of fibrolamellar hepatocellular carcinoma and has therefore been identified as a suitable diagnostic marker for and a driver of oncogenic activities in that cancer." (PMID 39458904, 2024). "This is evidence that PRKACA or the PKA signaling may regulate diverse genes/genetic pathways in different cancer types to accomplish the same biological processes and molecular functions." (PMID 39458904, 2024). "For example, it has been suggested that the PAK signaling and PRKACA activities could be inhibited upstream using β2 receptor blockade with propranolol as a strategy for the treatment of invasive cancer." (PMID 39458904, 2024). "A similar result was also observed for PRKACA in several cancers." (PMID 35246158, 2022). "PRKACA plays an important role in the development and progression of many cancers." (PMID 36569221, 2022). "PRKACA has also been reported to be involved in various cancers." (PMID 35432334, 2022). "With respect to therapy, PRKACA could be a target for the treatment of cancer." (PMID 39458904, 2024). "This suggests that PRKACA may perform as a biomarker for cancer and a prognostic indicator." (PMID 35646872, 2022). "Key targets such as TNF, PTGS2, PRKACA, HSP90AB1, RELA, and NFKBIA appeared to be involved in chemical carcinogenesis–receptor activation, pathways in cancer, IL-17 signaling pathway, cholinergic synapse pathway, and regulation of lipolysis in adipocytes." (PMID 39064924, 2024).